DCAF17 (DDB1 and CUL4 associated factor 17)
Description:
May function as a substrate receptor for CUL4-DDB1 E3 ubiquitin-protein ligase complex.
Synonyms: C2orf37; FLJ13096; C20orf37
Tractability: Antibody: UniProt predicts a signal peptide or a membrane-spanning region. PROTAC: ubiquitination databases record sites on it.
Gene: Protein-coding gene on chromosome 2 (171,434,217 to 171,485,052, forward strand). Ensembl gene ENSG00000115827.
Subcellular location: Membrane; Nucleus, nucleolus
Subcellular location (Human Protein Atlas): Nucleoplasm
Pathways (Reactome):
Metabolism of proteins: Neddylation
Gene Ontology:
Molecular function: protein binding
Biological process: spermatogenesis; protein ubiquitination
Cellular component: Cul4-RING E3 ubiquitin ligase complex; nucleoplasm; Cul4A-RING E3 ubiquitin ligase complex; Cul4B-RING E3 ubiquitin ligase complex; membrane; nucleolus
Genetic constraint (gnomAD): Loss-of-function variants: 32 observed, 50.27 expected, observed/expected ratio (o/e) 0.64, 90% interval 0.48 to 0.86. The upper end of that interval is the gene's LOEUF score, 0.86, which puts it in group 3 of 6, group 1 being the genes least tolerant of losing a copy. Missense variants: 506 observed, 566.17 expected, observed/expected ratio (o/e) 0.89, 90% interval 0.83 to 0.96. Synonymous variants: 191 observed, 194.67 expected, observed/expected ratio (o/e) 0.98, 90% interval 0.87 to 1.11.
Gene-disease validity (ClinGen):
ClinGen rates the evidence that DCAF17 causes each of these diseases.
Woodhouse-Sakati syndrome (autosomal recessive): Definitive. Woodhouse-Sakati syndrome is a multisystemic disorder characterized by hypogonadism, alopecia, diabetes mellitus, intellectual deficit and extrapyramidal signs with choreoathetoid movements and dystonia.
Homologues: Orthologues: chimpanzee DCAF17 (99% identical), macaque DCAF17 (98% identical), pig DCAF17 (93% identical), dog DCAF17 (93% identical), guinea pig DCAF17 (93% identical), rabbit DCAF17 (92% identical), mouse Dcaf17 (90% identical), rat Dcaf17 (90% identical), tropical clawed frog dcaf17 (62% identical), zebrafish dcaf17 (50% identical).
Diseases named in the same sentence as DCAF17 in open-access papers:
DCAF17 is named in the same sentence as 25 diseases in open-access papers, as found by Europe PMC text mining. Sharing a sentence is not in itself a finding about the gene and the disease. The quoted sentences say what the papers report.
Woodhouse-Sakati syndrome (15 papers, 2015 to 2026). "Woodhouse-Sakati Syndrome (WSS) is a rare autosomal recessive condition caused by biallelic pathogenic variants in the DCAF17 gene, with fewer than 200 cases reported in the literature." (PMID 39342163, 2024). "Woodhouse-Sakati syndrome (WSS) is a rare autosomal recessive multi-system genetic disease caused by loss of function mutations in the DCAF17 gene on chromosome 2q31.1." (PMID 36620807, 2022). "Woodhouse-Sakati syndrome (WSS) is a rare autosomal recessive neurodegenerative genetic disorder caused by mutations in the DCAF17 gene." (PMID 36185913, 2022). "Dcaf17 is critical for fertility and its mutation causes the Woodhouse-Sakati Syndrome in humans." (PMID 36509865, 2022). "Woodhouse-Sakati syndrome (WSS) is a rare autosomal recessive neuroendocrine disorder caused by pathogenic variants in the DDB1- and CUL4-associated factor 17 (DCAF17) gene." (PMID 42255876, 2026). "The DCAF17 gene is found on chromosome 2, encodes DDB1- and CUL4- associated factor 17, and is considered the cause of Woodhouse-Sakati syndrome, a rare neuroendocrine disorder that presents with neurological problems such as seizures and dystonia." (PMID 37024536, 2023). "Another more frequent NBIA disorder form according to our in-house database was Woodhouse-Sakati syndrome (WSS, MIM # 241080) due to biallelic DCAF17 variants." (PMID 35180557, 2022). "Woodhouse-Sakati syndrome (WSS, MIM 241080) is a rare neuroendocrine disease characterized by hair loss, hypogonadism, diabetes, hearing loss, and extrapyramidal syndrome, and is usually caused by mutations in the DCAF17 gene as an inherited disease." (PMID 34630532, 2021).
diabetes mellitus (7 papers, 2015 to 2025). A metabolic disorder characterized by abnormally high blood sugar levels due to diminished production of insulin or insulin resistance/desensitization. "Mutations in DCAF17 are associated with Woodhouse–Sakati syndrome, a rare disorder characterised by alopecia, hypogonadotropic hypogonadism, sensorineural hearing loss, diabetes mellitus, and extrapyramidal movement." (PMID 36568422, 2022). "Further tests revealed the presence of low insulin secretion, which suggests that β cell functional defects due to DCAF17 gene mutation are among possible mechanisms for the development of diabetes in WSS." (PMID 35002959, 2021). "Mutations in DCAF17 gene caused hypogonadism among other symptoms including diabetes and mental retardation in human." (PMID 32867693, 2020). "DCAF17 gene mutations may cause β cell functional defects, which may be one of the main mechanisms in the pathogenesis of diabetes in patients with WSS." (PMID 35002959, 2021). "We identified a WSS lineage in China with a novel DCAF17 gene mutation pattern and suggested that pancreatic β cell functional impairment might be one of the major mechanisms in the pathogenesis of WSS diabetes." (PMID 35002959, 2021).
Infertility (6 papers, 2018 to 2022). "To determine the molecular phenomenon underlying the infertility phenotype caused by disrupting Dcaf17, we performed RNA-sequencing-based gene expression profiling of 3-weeks and 8-weeks old Dcaf17 wild type and Dcaf17 disrupted mutant mice testes." (PMID 36509865, 2022). "This phenotype recapitulates hypogonadism and infertility, which are consistent findings in patients carrying DCAF17 mutations and indicates that this gene plays a role in mammalian gonadal development." (PMID 30744104, 2019). "Herein, RNA-Seq analysis showed that the reported infertility phenotype of Dcaf17 KO could be caused via disturbance of several mechanisms including protein proteolysis, chromatin modulation and gene expression." (PMID 36509865, 2022). "However, the infertility phenotype in Dcaf17 KO mice is caused mainly because of the defective germ cell development as shown by testicular histology, sperm analyses and TEM." (PMID 29907856, 2018). "The severe infertility phenotype observed in Dcaf17 KO male mice implicates indispensible function(s) of DCAF17 proteins during normal sperm development." (PMID 29907856, 2018). "DCAF17 plays an important role in mammalian gonadal development and infertility." (PMID 34630532, 2021). "It is however, not clear why loss of function mutations of DCAF17 lead to the complex clinical presentation of affected patients and why knock-out mice only develop infertility and no other signs typical of the human disorder." (PMID 30744104, 2019). "Breeding experiments of Dcaf17 homozygous KO mice revealed that Dcaf17−/− male mice are infertile." (PMID 29907856, 2018). "Normal mating behavior of Dcaf17 mutant mice and comparable anatomical structure, size and weight of Dcaf17−/− testes suggested that the infertility is not due to defective reproductive physiology, sex organ development or sexual behavior." (PMID 29907856, 2018).
hypogonadism (4 papers, 2015 to 2025). A disorder characterized by decreased function of the gonads. "A search of OMIM Clinical Synopsis fields using the term “hypogonadism” identified DCAF17 as the only candidate gene in the shared regions of homozygosity." (PMID 26664771, 2015).
male infertility (4 papers, 2018 to 2022). The inability of the male to effect fertilization of an ovum after a specified period of unprotected intercourse. "An additional mouse model generated by CRISPR/Cas9 approach determining loss of function mutation in exon 2 of Dcaf17, showed also female subfertility in addition to male infertility." (PMID 30744104, 2019). "Further to investigate how Dcaf17 deficiency leads to male infertility, we first examined the cauda epididymal sperm of WT and Dcaf17−/− adult mice." (PMID 29907856, 2018). "In conclusion, our studies on Dcaf17 KO mice successfully characterized the male infertility phenotype caused due to Dcaf17 deletion and demonstrated the importance of DCAF17 protein in maintaining normal spermiogenesis." (PMID 29907856, 2018). "Disruption of Dcaf17 in mice caused male infertility due to abnormality in sperm morphogenesis." (PMID 29907856, 2018). "DCAF17 is a substrate receptor in the ubiquitin CRL4 E3 Ligase complex, absence of which causes oligoasthenoteratozoospermia in mice resulting in male infertility." (PMID 36509865, 2022). "In our Dcaf17 mouse model, male infertility is defined by an abnormal morphology, reduced motility, and low sperm count." (PMID 36509865, 2022). "Despite normal female KO mice fertility, the male infertility phenotype of the Dcaf17 KO mice is attributed to the severe malformation and disorganization of specialized structures of the spermatozoa." (PMID 29907856, 2018). "Male infertility phenotype observed in Dcaf17 KO mice can be due to defective reproductive physiology, sex organ development or sexual behavior." (PMID 29907856, 2018). "In concordance with the reported male infertility phenotype in Dcaf17 KO mice, the majority of biological processes in downregulated DEGs at 3 weeks are involved in male reproductive processes such as spermatogenesis, cell projection organization, sperm motility, and cilium morphogenesis." (PMID 36509865, 2022). "Dcaf17 constitutive knockout mice showed male infertility due to abnormal sperm development." (PMID 30744104, 2019). "Targeted disruption of the Dcaf17 gene revealed that it is not essential for normal embryonic development and resulted in male infertility without other identifiable anatomical or behavioral abnormalities." (PMID 29907856, 2018). "Although Dcaf17 disruption did not have any effect on female fertility, Dcaf17 deletion led to male infertility due to abnormal sperm development." (PMID 29907856, 2018).
deafness (2 papers, 2022 to 2025). An inherited or acquired condition characterized by the complete loss of the ability to hear from one or both ears. "But, whether it was the homozygous missense matation in DCAF17 that caused embryonic dysplasia resulting in deafness remained to be further studied." (PMID 36568422, 2022).
Intellectual disability (2 papers, 2016 to 2025). "Monozygotic twins P6 and P7 from a consanguineous family with a novel homozygous variant p.Glu391GlyfsTer4 in the DCAF17 gene had a Turner syndrome-like phenotype and intellectual disability." (PMID 41393291, 2025). "Several genes related to intellectual disability (Dcaf17, Myst4, Park2, Rbfox1) were found to be hypo-methylated in male pups, and genes (Pfn1, Cntnap1, Drp2) related to normal function of the nervous system were hypo-methylated in female pups from the HMFA group." (PMID 27199632, 2016).
depression (1 paper, 2022). "We found less evidence that METTL8 and DCAF17 were involved in the depression and complex microbiota interaction." (PMID 36699448, 2022).
glioma (1 paper, 2024). A benign or malignant brain and spinal cord tumor that arises from glial cells (astrocytes, oligodendrocytes, ependymal cells). "Given that DCAF17, the host gene of hsa_circ_0001081, is linked to neurodegenerative diseases, exploring its circular variant’s role in GBM pathogenesis could provide novel and valuable insights in the field of glioma research." (PMID 39457549, 2024).
lung adenocarcinoma (1 paper, 2026). A carcinoma that arises from the lung and is characterized by the presence of malignant glandular epithelial cells. "Analysis of The Cancer Genome Atlas (TCGA) data revealed that seven DCAF genes (DCAF2, DCAF4, DCAF7, DCAF12, DCAF13, DCAF15, and DCAF17) were significantly upregulated in lung adenocarcinoma (LUAD)." (PMID 41047465, 2026).
cancer (1 paper, 2017). A tumor composed of atypical neoplastic, often pleomorphic cells that invade other tissues. "In the second dataset all the CGC genes (5/507) were classified as oncogenes by OncoScore and 4 (4/302) out of 5 nCan genes (ALMS1, DCAF17, GPD1L and WFS1) were classified as ‘non-cancer’ at the final time point, as expected." (PMID 28387367, 2017).
tumor (1 paper, 2017). "ANK2 and DCAF17 were extracted in tumor tissue of patients with different prognosis." (PMID 27564264, 2017).
DCAF17 also shares sentences with these, for which no sentence is quoted: Dystonia (4 papers); alopecia (3); hypogonadotropic hypogonadism (2); neuroendocrine disorder (2); oligoasthenoteratozoospermia (2); cystic fibrosis (1); developmental delay (1); hearing loss (1); neurodegenerative disease (1); Primary amenorrhea (1); secondary hypothyroidism (1); Turner syndrome (1); –Sakati syndrome (1).